RNU6-1184P (RNA, U6 small nuclear 1184, pseudogene)
Gene: Small nuclear RNA gene on chromosome 7 (147,831,770 to 147,831,877, forward strand). Ensembl gene ENSG00000207318.
Homologues: Orthologues: chimpanzee U6 (98% identical), macaque U6 (91% identical), dog U6 (69% identical), mouse Gm24716 (69% identical), dog U6 (65% identical), guinea pig U6 (59% identical). Paralogues in human: RNU6-38P (81% identical), RNU6-1067P (80% identical), RNU6-1145P (80% identical), RNU6-411P (80% identical), RNU6-1005P (79% identical), RNU6-151P (79% identical), RNU6-16P (79% identical), RNU6-247P (79% identical), RNU6-47P (79% identical), RNU6-616P (79% identical), RNU6-639P (79% identical), RNU6-86P (79% identical), and 1284 more.